MEG3 (maternally expressed 3)
Diseases named in the same sentence as MEG3 in open-access papers (continued):
Sharing a sentence is not in itself a finding about the gene and the disease.
cervical carcinoma (continued). "The results revealed HOTAIR, MALAT1 and MEG3 in cervical cancer patients was higher than that in healthy patients, indicating that lncRNA HOTAIR, MALAT1 and MEG3 levels in the exudates of vaginal lavage fluid samples have the potential of being the biomarkers for early diagnosis of cervical cancer." (PMID 34370713, 2021). "However, the inhibition of cervical cancer cell growth by MEG3 expression has not been validated in animal experiments, and its specific downstream proteins and mechanism of action are still unclear." (PMID 31320837, 2019). "Unlike normal adjacent tissues, cervical cancer tissues markedly express lower levels of MEG3." (PMID 28637507, 2017). "However, DZNep did not significantly affect MEG3 expression in cervical cancer cells, implying that histone methylation may not be a major mechanism of MEG3 inactivation." (PMID 28057015, 2017). "According to our data, the expression level of MEG3 does not differ between normal and CIN, but is significantly lower in patients with cervical cancer, both compared to the group of patients with normal cervical cancer and that of patients with CIN." (PMID 35682732, 2022). "However, MEG3 methylation was not significantly correlated with age, menopause, histology, differentiation, FIGO stage, tumor size, depth of invasion, or LVSI in cervical cancer." (PMID 28057015, 2017).
ovarian carcinoma (46 papers, 2016 to 2026). A malignant neoplasm originating from the surface ovarian epithelium. "In ovarian cancer, MEG3 overexpression has been repeatedly shown to decrease migration and invasion, further supporting our finding that MEG3 deficiency permits higher expression of MMPs and greater invasive activity." (PMID 41480643, 2026). "The regulative effect of MEG3 on miR-214 expression was associated with cisplatin resistance in ovarian cancer cells." (PMID 31488093, 2019). "Comparable findings have been reported in other contexts; for example, Shi and colleagues demonstrated that curcumin induced an increase in BAX and alterations in Bcl-2 family proteins in ovarian cancer, supporting the notion that phytochemical agents can enhance apoptosis via MEG3-associated axes." (PMID 41480643, 2026). "Among these transcripts, MEG3 has emerged as one of the most consistent tumor suppressors, with numerous studies associating its downregulation with poor prognosis and aggressive behavior in different malignancies, including ovarian carcinoma." (PMID 41480643, 2026). "In addition, MEG3 affected the epithelial-mesenchymal transition of ovarian cancer cells by sponging miR-219a-5p and regulating EGFR; low levels of MEG3 and miR-219a-5p were associated with a poor prognosis in patients with ovarian cancer." (PMID 40242248, 2025). "Upregulation of MEG3 expression is associated with a better prognosis in ovarian cancer patients." (PMID 38281945, 2024). "Evidence from clinical samples of epithelial ovarian cancer has shown that low MEG3 expression correlates with advanced stage disease, high grade pathology, and unfavorable survival outcomes, while higher levels of MEG3 are associated with improved therapeutic response and better prognosis." (PMID 41480643, 2026). "In other words, OXA-induced apoptosis is partly influenced by the MEG3 downregulation in ovarian cancer." (PMID 41480643, 2026). "Third, further mechanistic studies are needed to delineate the precise apoptotic and cell cycle signaling pathways under MEG3 control in ovarian cancer, as well as to map the microRNA and epigenetic networks that mediate its influence on metastasis." (PMID 41480643, 2026). "Integrating MEG3 modulation into ovarian cancer treatment strategies holds potential not only for improving the efficacy of conventional drugs but also for curbing metastasis and prolonging patient survival." (PMID 41480643, 2026). "When the different strands of evidence are integrated, a coherent model emerges in which MEG3 acts as a central mediator linking chemotherapy agents to multiple facets of ovarian cancer cell biology." (PMID 41480643, 2026). "After MEG3 siRNA the colony formation in ovarian cancer cell line was increased from 0.55 to 1.1 in DNC (p < 0.01), 0.5 to 0.95 in OXA (p < 0.05) and 0.3 to 0.6 in combination treatment (p < 0.05)." (PMID 41480643, 2026). "Transwell chamber migration assay was employed to investigate the possible role of MEG3 knockdown (down regulation) in migration of ovarian cancer cell lines after DNC, OXA and combination treatment." (PMID 41480643, 2026). "Overall, this investigation identifies MEG3 as a critical regulatory molecule as well as a promising therapeutic target in ovarian cancer management." (PMID 41480643, 2026). "Earlier studies in our research group found the anticancer properties of DNC are mediated by regulating the expression of lncRNA MEG3 and apoptotic-associated markers of Bcl-2 and BAX in ovarian cancer." (PMID 41480643, 2026). "Altogether, the data presented here reinforce MEG3 as a multifunctional tumor suppressor that orchestrates apoptosis, cell cycle arrest, invasion, and therapeutic response in ovarian cancer cells treated with DNC and OXA." (PMID 41480643, 2026). "First, they support the notion that MEG3 can be harnessed as a biomarker for both prognosis and prediction of chemotherapy response in ovarian cancer patients." (PMID 41480643, 2026).
ovarian carcinoma (continued). "HOXA11-AS, downregulated in epithelial ovarian cancer, likely modulates transcriptional pathways, complementing MEG3’s role in metastasis control." (PMID 40242248, 2025). "Further, several lncRNAs have been linked with p-53 in ovarian cancer, of which H19, MALAT1, PVT1 and LINC-ROR are upregulated while MEG3 and PANDA are known to be downregulated." (PMID 39912983, 2025). "Another study reported that MEG3 overexpression inhibited the cellular viability and invasion while promoting apoptosis in ovarian cancer through sponging miR-205-5p." (PMID 40242248, 2025). "Second, MEG3 inhibited the progression of ovarian cancer by sponging miR-30e-3p and regulating LAMA4 expression." (PMID 40242248, 2025). "THC most likely inhibits the ovarian cancer cells' cisplatin resistance by controlling the extracellular vesicle‐mediated deposition of maternally expressed 3 (MEG3) and miR‐214." (PMID 41179371, 2025). "Knocking down MEG3 and miR-219a-5p in ovarian cancer cells increased the cellular viability, proliferation, invasion, and migration, and decreased apoptosis." (PMID 40242248, 2025). "Overexpressing MEG3 in ovarian cancer endothelial cells decreased tube formation through modulating the miR-376a/RASA1 axis." (PMID 40242248, 2025). "First, MEG3 was reported to regulate angiogenesis in ovarian cancer endothelial cells by sponging miRNA-376a and YBX1, with significantly lower expression in ovarian cancer endothelial cells than that in normal ovarian endothelial cells." (PMID 40242248, 2025). "Then, we conducted a CCK-8 assay and found that MEG3 overexpression significantly reduced the proliferation of ovarian cancer cells." (PMID 38281945, 2024). "Function assays were used to detect the effect of MEG3 on the malignant phenotype of ovarian cancer." (PMID 38281945, 2024). "Here, we investigated the expression level of MEG3 in ovarian cancer and observed that increased MEG3 expression prolonged the overall survival (OS) of patients." (PMID 38281945, 2024). "In this study, we discovered that MEG3 was downregulated in various cancers, with the most apparent downregulation in ovarian cancer." (PMID 38281945, 2024). "More importantly, this study comprehensively verified the regulatory effect of the MEG3/hsa-miR-885-5p/VASH1 axis on the development of ovarian cancer." (PMID 38281945, 2024). "These researchers further observed decreased expression of HOTAIR, bcl-2, and H19, along with overexpression of MEG3, after treating ovarian cancer cells with DNC, indicating that curcumin exerts its anticancer effects via multiple pathways." (PMID 39830662, 2024). "Compared with normal ovarian epithelial cells, MEG3 expression was generally reduced in ovarian cancer cells." (PMID 38281945, 2024). "To verify the effect of MEG3 on the biological phenotype of ovarian cancer cells, we established MEG3 overexpression and knockdown cell lines in SKOV3 and A2780 using lentivirus infection, respectively, and proved the transfection efficiency using qRT‒PCR." (PMID 38281945, 2024). "MEG3 positively regulated the expression level of VASH1 in ovarian cancer cells through hsa-miR-885-5p, exerting an antitumor effect." (PMID 38281945, 2024). "Subsequently, we found that MEG3 expression was decreased in pancancer tissues compared to normal tissues, and the fold change was highest in ovarian cancer." (PMID 38281945, 2024). "LncRNA MEG3 can be a promising biomarker for ovarian cancer diagnosis and treatment by modifying the epithelial-mesenchymal transsition of ovarian cancer cells through sponging miR-219a-5p and modulating EGFR." (PMID 35109842, 2022). "MEG3 overexpression causes anti-proliferative and cytotoxic effects in the OVCAR3 ovarian cancer cell line." (PMID 34204445, 2021). "MEG3, SNHG16, MNX1-AS1, and ZFAS1 are confirmed to be associated with ovarian cancer in the Lnc2cancer database, and their PMIDs are 28175963, 29461589, 29271994, and 28154416, respectively." (PMID 33980147, 2021).
ovarian carcinoma (continued). "MEG3 regulates the PTEN gene in ovarian cancer cells to prohibit cell proliferation, promote apoptosis and block cell cycle progression." (PMID 34461858, 2021). "It is worthy of note that the expression of MEG3 is overexpressed in the tumor samples of ovarian cancer, and downregulated in the anisomycin-treated ovarian cancer stem cells." (PMID 34069546, 2021). "Results of in vitro studies also pointed out that lowly expressed MEG3 in ovarian cancer cells was relevant to hypermethylation in the promoter of MEG." (PMID 32618397, 2020). "MEG3 expression is also decreased in ovarian cancer compared to normal tissue, and its promoter is highly methylated." (PMID 32295169, 2020). "The decrease of cisplatin resistance in ovarian cancer cells by curcumin is probably through regulating extracellular vesicle-induced transfer of miR-214 and maternally expressed 3 (MEG3)." (PMID 33148295, 2020). "Due to recent studies showing a role for phosphatase and tensin homologue (PTEN) in mediating MEG3 tumor suppressor activity in ovarian cancer cells, we evaluated PTEN expression in stably transfected HEY pcDNA and pMEG3 cells." (PMID 32295169, 2020). "For instance, our model identified MEG3 overexpression as a predictor of cisplatin sensitivity, which is consistent with previous findings that lung and ovarian cancer patients with MEG3 over-expression have better response to cisplatin treatment." (PMID 30093685, 2018). "Additional studies on the effects of NEAT1, MALAT1 and MEG3 aberrant expression in CCs should bring critical insights into their function during oocyte maturation and in ovarian carcinoma." (PMID 29396444, 2018). "In this study, we found that the expression of Meg3 was lower in epithelial ovarian carcinoma, and has potential to be considered as a biomarker for ovarian cancer." (PMID 28423647, 2017). "Our comprehensive study identified three novel lncRNA (DNM3OS, MEG3, and MIAT) associated with ovarian cancer EMT." (PMID 29150601, 2017). "For example, MEG3 was recently reported to influence STAT3 expression by altering miR-21 expression in ovarian cancer." (PMID 28637507, 2017). "ROC analysis results showed that ROC plots for MEG3 for benign tumor vs ovarian cancer, normal vs ovarian cancer AUCs of 0.727, and 0.763, respectively (P < 0.05)." (PMID 28423647, 2017). "In the DisLncPri predicting result list, we found 4 novel lncRNAs in top 20 (GAS5 at 1, MALAT1 at 4, MEG3 at 6 and HOTAIR at 9) that were recently associated with ovarian cancer." (PMID 27992375, 2017). "Reannotation of microarray probe sets showed that DIO3OS, DNM3OS, MIAT, and MEG3 lncRNA were detected in the two ovarian cancer subtypes at levels similar to known protein coding EMT-linked genes." (PMID 29150601, 2017). "Ectopic expression of MEG3 was reported to suppress the proliferation and growth of ovarian cancer cells and promote apoptosis." (PMID 27992375, 2017). "However, little is known about the role of MEG3 in the development of chemo resistant in ovarian cancer." (PMID 41480643, 2026). "The combination of DNC and OXA holds promise as an effective therapeutic strategy in OC, and MEG3 may serve as a potential biomarker and therapeutic target, particularly in drug-resistant ovarian cancer." (PMID 41480643, 2026). "This study investigated the impact of siRNA-mediated MEG3 silencing in the context of dendrosomal nanocurcumin (DNC) and Oxaliplatin (OXA) treatments on ovarian cancer cell lines, focusing on the expression of genes associated with apoptosis and metastasis, including Bcl-2, BAX, MMP-2, and MMP-9." (PMID 41480643, 2026). "The present investigation highlights MEG3 as a central determinant of ovarian cancer cell responses to DNC, OXA and their combination, revealing that the tumor-suppressive lncRNA actively governs gene expression programs linked to apoptosis, invasion, and cell-cycle regulation." (PMID 41480643, 2026).
ovarian carcinoma (continued). "Multiple studies have investigated the function of the lncRNA MEG3 in ovarian cancer." (PMID 40242248, 2025). "Curcumin increases the expression of MEG3 in ovarian cancer by bringing about DNA hypomethylation." (PMID 39912983, 2025). "In addition, silencing MEG3 results in faster proliferation, stronger migration, and delayed apoptosis of ovarian cancer cells." (PMID 38281945, 2024). "Overall, our research revealed the role of MEG3 in obstructing the progression of ovarian cancer from a new perspective, which may provide novel target insights for the future treatment of ovarian cancer." (PMID 38281945, 2024). "MEG3 knockdown facilitated the malignancy of ovarian cancer in both in vivo and in vivo models." (PMID 38281945, 2024). "XIST and MEG3 have been reported to suppress cell migration and invasion in ovarian cancer." (PMID 38571514, 2024). "The novelty of this study lies in revealing a new mechanism of MEG3 in human ovarian cancer cells." (PMID 38281945, 2024). "MEG3 inhibited the proliferation, migration, and invasion of ovarian cancer cells." (PMID 38281945, 2024). "MEG3 is expected to become a therapeutic target for ovarian cancer." (PMID 38281945, 2024). "Overall, our study confirms the inhibitory effect of MEG3 in ovarian cancer and reveals new regulatory mechanisms of MEG3 from the perspectives of m6A methylation and ceRNA, and our results are expected to provide new targets for the treatment of ovarian cancer." (PMID 38281945, 2024). "In summary, research results indicated that MEG3 inhibited ovarian cancer cell malignancy." (PMID 38281945, 2024). "In summary, our research results indicate that MEG3 expression is reduced in ovarian cancer." (PMID 38281945, 2024). "A group from China Medical University revealed that MEG3 may be a potential biomarker for epithelial ovarian cancer (EOC) and acts as a tumor suppressor in EOC by modulating autophagy-related 3 (ATG3) activity and triggering autophagy." (PMID 36544907, 2022). "However, we discovered that MEG3 was upregulated in platinum-resistant ovarian cancer patients, which was most probably due to the difference in the disease type and therapy regimen." (PMID 35592674, 2022). "When compared to normal tissue, there is a decreased expression of MEG3 in ovarian cancer." (PMID 34204445, 2021). "In ovarian cancer stem cells, MEG3 also interacts with miR-421." (PMID 34069546, 2021). "Indeed, one of the most interesting mechanisms of action reported for MEG3 is the positive regulation of PTEN expression in ovarian cancer cells." (PMID 32295169, 2020). "In addition, MEG3 is downregulated in ovarian cancer tissues, and overexpression of MEG3 inhibits cell proliferation, migration, and invasion and promotes apoptosis in ovarian cancer cell lines." (PMID 32684827, 2020). "We also investigated MEG3 function in ovarian cancer biology." (PMID 32295169, 2020). "However, the potential clinical implications of dysregulated MEG3 expression in ovarian cancer is still unclear." (PMID 32295169, 2020). "Furthermore, the expression of Meg3 in metastatic omentum tumors was even lower than in primary ovarian carcinoma." (PMID 28423647, 2017). "In addition, ectopic expression of MEG3 has inhibited the proliferation and the growth of ovarian cancer cells and enhanced their apoptosis." (PMID 27664137, 2017). "Nude mice xenograft assays showed that overexpression of Meg3 could reduce tumorigenesis of ovarian cancer cells in vivo." (PMID 28423647, 2017). "Additionally, genome-wide mapping of MEG3 binding sites revealed that 73% of EMT-linked pathway genes that were deregulated in EMT in TCGA cohort are bound by MEG3, suggesting MEG3 is likely involved in EMT in ovarian cancer." (PMID 29150601, 2017). "The silenced MEG3 expression in ovarian cancer is also due to promoter region hypermethylation which may also contribute to the progression of cancer development." (PMID 29069869, 2017).